SLCO1B3 (solute carrier organic anion transporter family member 1B3)
Description:
Mediates the Na(+)-independent uptake of organic anions. Shows broad substrate specificity, can transport both organic anions such as bile acid taurocholate (cholyltaurine) and conjugated steroids (17-beta-glucuronosyl estradiol, dehydroepiandrosterone sulfate (DHEAS), and estrone 3-sulfate), as well as eicosanoid leukotriene C4, prostaglandin E2 and L-thyroxine (T4). Hydrogencarbonate/HCO3(-) acts as the probable counteranion that exchanges for organic anions. Shows a pH-sensitive substrate specificity towards sulfated steroids, taurocholate and T4 which may be ascribed to the protonation state of the binding site and leads to a stimulation of substrate transport in an acidic microenvironment. Involved in the clearance of bile acids and organic anions from the liver. Can take up bilirubin glucuronides from plasma into the liver, contributing to the detoxification-enhancing liver-blood shuttling loop. Transports coproporphyrin I and III, by-products of heme synthesis, and may be involved in their hepatic disposition. May contribute to regulate the transport of organic compounds in testes across the blood-testis-barrier (Probable). Can transport HMG-CoA reductase inhibitors (also known as statins) such as pitavastatin, a clinically important class of hypolipidemic drugs. May play an important role in plasma and tissue distribution of the structurally diverse chemotherapeutic drugs methotrexate and paclitaxel. May also transport antihypertension agents, such as the angiotensin-converting enzyme (ACE) inhibitor prodrug enalapril, and the highly selective angiotensin II AT1-receptor antagonist valsartan, in the liver.
Synonyms: LST-2; OATP-8; OATP1B3; OATP8; SLC21A8; HBLRR; LST-3TM13; LST3
Tractability: Small molecule: a structure with a bound ligand is known. Antibody: UniProt places it where antibodies can reach, with high confidence; its Gene Ontology location is reachable by antibodies, with high confidence; UniProt predicts a signal peptide or a membrane-spanning region; the Human Protein Atlas places it where antibodies can reach. PROTAC: ubiquitination databases record sites on it; a small molecule that binds it is known.
Target class: Electrochemical transporter; SLC superfamily of solute carriers; SLC21/SLCO family of organic anion transporting polypeptides; Transporter
Safety:
Unwanted effects reported when the protein is acted on. In parentheses: how it was acted on, where the effect was seen, and who reports it.
adverse drug reactions (source: ClinPGx)
anemia (source: ClinPGx)
anemia and thrombocytopenia (source: ClinPGx)
clearance of docetaxel (source: ClinPGx)
exposure to active mycophenolic acid (source: ClinPGx)
leukopenia (source: ClinPGx)
Gene: Protein-coding gene on chromosome 12 (20,810,691 to 20,916,911, forward strand). Ensembl gene ENSG00000111700.
Subcellular location: Basolateral cell membrane; Basal cell membrane
Subcellular location (Human Protein Atlas): Plasma membrane
Pathways (Reactome):
Metabolism: Heme degradation; Recycling of bile acids and salts
Disease: Defective SLCO1B3 causes hyperbilirubinemia, Rotor type (HBLRR)
Drug ADME: Atorvastatin ADME
Transport of small molecules: Organic anion transport by SLCO transporters
Gene Ontology:
Molecular function: transmembrane transporter activity; bile acid transmembrane transporter activity; secondary active transmembrane transporter activity
Biological process: bile acid and bile salt transport; heme catabolic process; sodium-independent organic anion transport; transmembrane transport; xenobiotic metabolic process
Cellular component: basal plasma membrane; basolateral plasma membrane; plasma membrane; membrane
Genetic constraint (gnomAD): Loss-of-function variants: 27 observed, 32.35 expected, observed/expected ratio (o/e) 0.83, 90% interval 0.61 to 1.15. The upper end of that interval is the gene's LOEUF score, 1.15, which puts it in group 5 of 6, group 1 being the genes least tolerant of losing a copy. Missense variants: 532 observed, 468.59 expected, observed/expected ratio (o/e) 1.14, 90% interval 1.06 to 1.22. Synonymous variants: 170 observed, 160.69 expected, observed/expected ratio (o/e) 1.06, 90% interval 0.93 to 1.2.
Homologues: Orthologues: chimpanzee SLCO1B3 (99% identical), macaque SLCO1B3 (88% identical), dog SLCO1B2 (71% identical), mouse Slco1b2 (65% identical), rat Slco1b2 (63% identical), tropical clawed frog slco1b3 (45% identical), Drosophila melanogaster Oatp30B (28% identical). Paralogues in human: SLCO1B1 (78% identical), SLCO1C1 (44% identical), SLCO1A2 (38% identical), SLCO3A1 (31% identical), SLCO2B1 (29% identical), SLCO2A1 (29% identical), SLCO5A1 (29% identical), SLCO4C1 (26% identical), SLCO4A1 (25% identical), SLCO6A1 (21% identical).
Diseases named in the same sentence as SLCO1B3 in open-access papers:
SLCO1B3 is named in the same sentence as 81 diseases in open-access papers, as found by Europe PMC text mining. Sharing a sentence is not in itself a finding about the gene and the disease. The quoted sentences say what the papers report.
prostate carcinoma (21 papers, 2011 to 2024). A carcinoma that arises from epithelial cells of the prostate gland. "The resistance to Taxane therapy is induced by the OATP1B3 transport protein in prostate cancer cells encoded by SLCO1B3." (PMID 37858151, 2023). "We thus made the hypothesis that gene polymorphisms occurring in CYP17A1, SLCO2B1, and SLCO1B3 could influence AA antitumor activity in advanced prostate cancer." (PMID 36839973, 2023). "Similarly, carriers of the T allele in the SLCO1B3 SNP rs4149117, c.334T>G had a 76% increased risk of prostate cancer-specific mortality." (PMID 32806706, 2020). "The liver-type OATP1B3 (lt-OATP1B3) is an androgen transporter, and polymorphic variations in the SLCO1B3 gene are associated with poor overall survival from diagnosis, poor progression-free survival on androgen deprivation therapy biochemical recurrence and prostate cancer-specific mortality 25-29." (PMID 38213719, 2024). "The organic anion polypeptide 1B3 (OATP1B3, encoded by SLCO1B3) transporter has been shown to transport androgens into prostate cancer cells." (PMID 34031488, 2021). "Since p300-mediates expression of SLCO1B3, we first examined the effect of antiandrogens on SLCO1B3 expression in two well characterized AR-positive prostate cancer cell lines (22Rv1 & LNCaP)." (PMID 34031488, 2021). "We have recently discovered that chetomin is a potent inducer of SLCO1B3 transcription in prostate cancer cells." (PMID 34031488, 2021). "SLCO1B3 is frequently overexpressed in prostate cancer, and docetaxel and testosterone are both OATP1B3 substrates." (PMID 32989230, 2020). "We also demonstrated that SLCO1B3 expression levels are significantly related to the Gleason score in prostate cancer." (PMID 21625523, 2011). "While ct-SLCO1B3 has been previously investigated as an EV-derived tumor marker in both squamous cell carcinoma and colorectal cancer 6, 7, its role as a potential liquid biopsy EV-derived marker in prostate cancer has yet to be explored." (PMID 38213719, 2024). "However, other notable trends were SLCO2B1 decreased expression by stage in pancreatic cancer, SLCO1B3 increased frequency by stage in prostate cancer, and SLCO1B1 decreased expression by stage in liver cancer." (PMID 21625523, 2011). "Even if afatinib has not been described as a good substrate of this transporter, we cannot exclude that PXR-mediated intracellular accumulation of afatinib may also be due to the induction of other influx pumps that are expressed in prostate cancer such as SLCO1B3." (PMID 34298852, 2021). "Our results provide evidence for EV-contained ct-SLCO1B3 and ABCC3 as novel, EV-based tumor markers for prostate cancer progression." (PMID 38213719, 2024). "The presence of SNPs in genes involved in the membrane transport of testosterone and dehydroepiandrosterone (DHEA), namely SLCO2B1 and SLCO1B3, has been reported as having an influence on the efficacy of androgen deprivation therapy (ADT) in prostate cancer." (PMID 36839973, 2023). "Prostate cancer cells (22Rv1, LNCaP, and VCAP) were treated with anti-androgens and assessed for SLCO1B3 expression by qPCR analysis." (PMID 34031488, 2021). "This study investigated whether ct-SLCO1B3 and ABCC3 can be detected in prostate cancer-derived EVs." (PMID 38213719, 2024). "Moreover, mRNA expression levels of SLCO1B1, SLCO1B3, SLCO2B1 and SLCO4C1 were found to be higher in castration-resistant prostate cancer metastases as compared to in untreated prostate cancer." (PMID 36839686, 2023).
colon cancer (19 papers, 2011 to 2026). "SLCO1B3 is associated with colon cancer and is involved in drug uptake into cancer cells." (PMID 26894861, 2016). "While Lt-OATP1B3 (the translated product of Lt-SLCO1B3) was mostly found as a membrane-bound protein on the cell surface, Ct-OATP1B3 (the translated product of Ct-SLCO1B3) was mainly detected in the cytoplasm of colon cancer cells." (PMID 34526411, 2021). "In addition, cancer-type OATP1B3 (Ct-OATP1B3), a tumor-specific isoform protein produced by selective splicing of the SLCO1B3 gene, is highly expressed in tissues such as colon cancer, while it is hardly expressed in normal tissues." (PMID 40723888, 2025). "Importantly, Ct-SLCO1B3 was detected significantly higher than Lt-SLCO1B3 in both human colon cancer tissues and cells." (PMID 34526411, 2021). "Importantly, Ct-SLCO1B3 was detected significantly higher than Lt-SLCO1B3 in human colon cancer tissues." (PMID 34526411, 2021). "Protein expression generally did not correspond to mRNA expression for the remaining markers, i.e. GRM8, LY6G6D/F, SLCO1B3 and TLR4, indicating that protein levels for these markers are likely regulated after translation in this set of colon cancer cells." (PMID 26894861, 2016). "Ectopic expression of the solute carrier organic anion transporter family member 1B3 (OATP1B3) was detected in solid tumors of non-hepatic origin, particularly in pancreatic cancer and colon cancer." (PMID 35928153, 2022).
breast carcinoma (17 papers, 2011 to 2025). "In conclusion, BRCA1 (Pro871Leu), ERCC1 (Asn118Asn), CYP1B1 (Leu432Val), and SLCO1B3 (rs11045585) are associated with response to NCT in our cohort of breast cancer patients." (PMID 26180747, 2015). "SLCO1B3 acts as a tumor suppressor by inhibiting the development and progression of breast cancer, while ZEB2 promotes the growth and metastasis of liver cancer." (PMID 41187171, 2025). "Our study showed that 80% of breast cancer tissues were positive for SLCO1B3 expression, and 24% of them were strongly positive." (PMID 33436824, 2021). "The role of organic anion transporting polypeptide 1B3 (SLCO1B3) in breast cancer is still controversial." (PMID 33436824, 2021). "The high expression of SLCO1B3 in breast cancer tissues was negatively correlated with breast cancer stage, lymph node metastasis status, and histological grade." (PMID 33436824, 2021). "The cellular function assay showed that the ability of cell proliferation, migration and invasion was significantly enhanced after knockdown of SLCO1B3 expression in breast cancer cell lines." (PMID 33436824, 2021). "In contrast, high SLCO1B3 expression (HR = 0.318, P = 0.001) was a predictor of favorable OS for breast cancer patients." (PMID 33436824, 2021). "The result from in vitro CCK-8 assay indicated that knockdown of SLCO1B3 expression promoted the proliferation of breast cancer cell MDA-MB-231, and the difference was statistically significant (P < 0.001)." (PMID 33436824, 2021). "In contrast, the ability of cell proliferation, migration and invasion was significantly reduced after overexpress the SLCO1B3 in breast cancer cell lines (P < 0.05)." (PMID 33436824, 2021). "Further studies are needed to characterize the mechanism by which SLCO1B3 regulates the development of breast cancer." (PMID 33436824, 2021). "Our study provided basis for further studies, and highlighted the usefulness of SLCO1B3 as a potential biomarker for diagnosis, treatment, and prognosis evaluation in breast cancer." (PMID 33436824, 2021). "High level of SLCO1B3 expression can inhibit the proliferation, invasion and migration of breast cancer cells, leading to better prognosis of patients." (PMID 33436824, 2021). "This study is the first to report ERCC1, BRCA1 and SLCO1B3 as markers of response to NCT in breast cancer." (PMID 26180747, 2015). "In addition, the mechanism by which SLCO1B3 inhibits the occurrence and development of breast cancer is still unclear, which needs to be further explored." (PMID 33436824, 2021). "However, in this study, SLCO1B3 was not only highly expressed on the cell membrane and cytoplasm of normal breast tissues, but was also expressed on the same locations of breast cancer tissues." (PMID 33436824, 2021). "In vitro study indicated that SLCO1B3 can inhibit the proliferation, migration, and invasion of breast cancer cells, suggesting that SLCO1B3 may play a suppressive role in the development of breast cancer." (PMID 33436824, 2021). "The in vitro study indicated that SLCO1B3 may be involved in the proliferation, migration and metastasis of tumor cells, and may play a role in suppressing tumor during the progression of breast cancer." (PMID 33436824, 2021). "SLCO1B3 may serve a potential biomarker for breast cancer diagnosis, treatment and prognosis evaluation." (PMID 33436824, 2021). "SLCO1B3 will become a potential biomarker for breast cancer diagnosis and prognosis assessment." (PMID 33436824, 2021). "However, we also performed the multivariate COX analysis to adjust all potential covariates, and the results strengthened the prognostic significance of SLCO1B3 expression for breast cancer patients." (PMID 33436824, 2021). "However, immunohistological analysis correlated with clinicopathological parameters in 102 breast carcinomas revealed SLCO1B3 expression is inversely correlated with tumour size and is associated with a decreased risk of recurrence." (PMID 32388639, 2020).
breast carcinoma (continued). "In contrast, another study examining SLCO1B3 expression in 102 breast carcinoma samples using IHC found SLCO1B3 expression in 50% of samples, and where immune reactivity was found this was inversely correlated to tumour size and was associated with a lower incidence of BC recurrence." (PMID 32388639, 2020). "Therefore, SLCO1B3 is a potential indicator for breast cancer prognosis, and its function may be related to estrogen status in breast cancer." (PMID 33436824, 2021). "The role of SLCO1B3 in breast cancer may be related to estrogen." (PMID 33436824, 2021). "This study mainly explored the relationship between SLCO1B3 and breast cancer, and provided more in vitro evidence to illustrate the role of SCLO1B3 in the development, invasion, and metastasis of breast cancer." (PMID 33436824, 2021). "The previous studies also investigated the role of SLCO1B3 in breast cancer, but there was no unified conclusion." (PMID 33436824, 2021). "In contrast, there was a significant relationship between high SLCO1B3 expression and better survival outcome after excluding breast cancer patients without adjuvant treatments (e.g.: adjuvant chemotherapy and endocrine therapy)." (PMID 33436824, 2021). "However, we did not observe the effect of SLCO1B3 for the apoptotic ability of breast cancer cells." (PMID 33436824, 2021). "Moreover, we could not evaluate the impact of SLCO1B3 expression on cancer-specific survival (CSS) in breast cancer patients since the relevant data was scarce." (PMID 33436824, 2021). "Despite previously published reports, SLCO1B3, SLCO2B1, and SLCO1B1 were not highly expressed in our breast cancer samples." (PMID 21625523, 2011). "Moreover, OATP1A2/SLCO1A2 and OATP1B3/SLCO1B3 mRNA and protein expression was significantly higher in malignant breast cancer tissue as compared to the surrounding non-malignant tissue." (PMID 36839686, 2023).
hepatocellular carcinoma (17 papers, 2016 to 2025). A malignant tumor that arises from hepatocytes. "Based on this analysis, Caco-2 (low Ct-SLCO1B3 mRNA expression), DLD1 and T84 (high Ct-SLCO1B3 mRNA expression) cells were used for further reporter gene analyses together with the hepatocellular carcinoma cell lines HepG2 and Hep3B." (PMID 36986600, 2023). "The luciferase activity of the different Lt- and Ct-SLCO1B3 reporter gene constructs was analyzed in the hepatocellular carcinoma cell lines HepG2 and Hep3B and in the colorectal carcinoma cell lines DLD1, T84 and Caco-2." (PMID 36986600, 2023). "This may be one reason for the relatively low reporter gene activity of the Lt-SLCO1B3 constructs in the hepatocellular carcinoma cell lines." (PMID 36986600, 2023). "In hepatocellular carcinoma, the elevated expression of HNF3β represses SLCO1B3 expression." (PMID 36839686, 2023). "Analysis of the TCGA Liver Hepatocellular Carcinoma dataset (TCGA’s Pan-Cancer Atlas) revealed a low mutation and amplification frequency in HCC for SLCO1B1 (0.57% vs. 0.29%), SLCO1B3 (0.86% vs. 0.29%) and SLCO2B1 (0.57% vs. 0.86%)." (PMID 40734706, 2025). "Analysis of the TCGA Liver Hepatocellular Carcinoma dataset (TCGA’s Pan-Cancer Atlas) revealed a low mutation and amplification frequency in HCC for SLCO1B1 (0.57% vs. 0.29%), SLCO1B3 (0.86% vs. 0.29%), and SLCO2B1 (0.57% vs. 0.86%), respectively." (PMID 40734706, 2025). "Thus, the inhibition of HNF3β may provide means to increase SLCO1B3 expression and increase drug therapy efficacy in hepatocellular carcinoma." (PMID 36839686, 2023). "However, HepaRG cells remain transformed hepatoma cells, which express at low level certain detoxifying proteins present in human hepatocytes, such as the cytochromes P-450 1A2, 2D6 and 2E1 and the drug transporters OATP1B3 (SLCO1B3) and bile salt export pump (BSEP/ABCB11)." (PMID 30469356, 2018). "Furthermore, it has been demonstrated that in 60% of investigated hepatocellular carcinoma samples, the Lt-SLCO1B3 mRNA and the respective Lt-OATP1B3 protein are downregulated." (PMID 36986600, 2023). "However, the expression of SLCO1B3 was differently regulated by the RAR agonist, as the expression in the hepatoma cells was increased, whereas, in the hepatocytes, the expression was decreased." (PMID 36839686, 2023). "In contrast, in two SLCO1B3-negative cell lines, i.e., hepatocellular carcinoma HepG2 and colorectal adenocarcinoma cells, Caco-2 cells, and, in the kidney, CpG dinucleotides were hypermethylated." (PMID 36839686, 2023).